SOD3 (superoxide dismutase 3)
Description:
Protect the extracellular space from toxic effect of reactive oxygen intermediates by converting superoxide radicals into hydrogen peroxide and oxygen.
Synonyms: EC-SOD
Tractability: Small molecule: it has a high-quality binding pocket. Antibody: its Gene Ontology location is reachable by antibodies, with high confidence; UniProt places it where antibodies can reach, with medium confidence; UniProt predicts a signal peptide or a membrane-spanning region.
Target class: Enzyme
Gene: Protein-coding gene on chromosome 4 (24,789,912 to 24,800,848, forward strand). Ensembl gene ENSG00000109610.
Subcellular location: Secreted, extracellular space; Golgi apparatus, trans-Golgi network
Pathways (Reactome):
Cellular responses to stimuli: Detoxification of Reactive Oxygen Species; NFE2L2 regulating anti-oxidant/detoxification enzymes
Gene Ontology:
Molecular function: molecular adaptor activity; protein binding; superoxide dismutase activity; copper ion binding; metal ion binding
Biological process: acute inflammatory response; nitric oxide metabolic process; removal of superoxide radicals; superoxide metabolic process
Cellular component: extracellular exosome; extracellular region; Golgi lumen; cytoplasm; Golgi apparatus
Genetic constraint (gnomAD): Loss-of-function variants: 10 observed, 6.07 expected, observed/expected ratio (o/e) 1.65, 90% interval 0.95 to 1.95. That is too few expected variants to judge how well the gene tolerates losing a copy. Missense variants: 379 observed, 273.65 expected, observed/expected ratio (o/e) 1.38, 90% interval 1.27 to 1.51. Synonymous variants: 188 observed, 122.1 expected, observed/expected ratio (o/e) 1.54, 90% interval 1.37 to 1.74.
Homologues: Orthologues: chimpanzee SOD3 (100% identical), macaque SOD3 (94% identical), pig SOD3 (75% identical), guinea pig SOD3 (72% identical), dog SOD3 (70% identical), mouse Sod3 (66% identical), rat Sod3 (66% identical), tropical clawed frog sod3 (45% identical), zebrafish sod3b (38% identical), zebrafish sod3a (36% identical). Paralogues in human: CCS (28% identical), SOD1 (25% identical).
Diseases named in the same sentence as SOD3 in open-access papers:
SOD3 is named in the same sentence as 215 diseases in open-access papers, as found by Europe PMC text mining. Sharing a sentence is not in itself a finding about the gene and the disease. The quoted sentences say what the papers report.
Hypertension (23 papers, 2010 to 2025). The presence of chronic increased pressure in the systemic arterial system. "A loss of function mutation of SOD3 in rats induced chronic renal failure that develops during the first 5 months of age and this is accompanied by severe systemic hypertension and moderate LV hypertrophy." (PMID 37265567, 2023). "Variations in the SOD2 and SOD3 genes can participate in susceptibility to breast cancer, chronic obstructive pulmonary disease in adults and children, preeclampsia, insulin resistance, type 2 diabetes, and arterial hypertension." (PMID 38133349, 2023). "SOD3 heterozygous knockout (SOD3(+/−)) mice exhibited an aggravated angiotensin-stimulated hypertension due to reduced bioavailability of nitric oxide (NO) in the vascular wall." (PMID 41154722, 2025). "It has been demonstrated that ATP7A, a copper-transporting protein, plays a critical role in Ang II-induced hypertension and the regulation of endothelial function by modulating SOD3 activity and vascular superoxide anion production." (PMID 39267854, 2024). "Activity and/or expression of copper-bound SOD3 was reported to be decreased in animal models and humans with hypertension, HF, and coronary heart disease." (PMID 35277059, 2022). "Consistently, Atp7a-knockout worsens angiotensin II-induced hypertension by blunting SOD3 activity in mice." (PMID 35277059, 2022). "The most common pathological conditions in contemporary culture, such as inflammatory bowel disease, obesity and its consequences—diabetes and hypertension—and chronic obstructive pulmonary disease, have been linked to changes in SOD (SOD1 and SOD3) activity and its expression." (PMID 40867576, 2025). "For instance, in angiotensin II (Ang II)-induced hypertension, the antioxidant 1 copper chaperone (Atox1) raises blood pressure by reducing extracellular oxygen anions and increasing the expression and activity of vascular superoxide dismutase 3 (SOD3)." (PMID 39267854, 2024). "There was a significant association (p < 0.05) of SOD3 and GSTp1 values with ferritin and Zn in diabetes alone, diabetes with hypertension, and no co-morbidities subgroups." (PMID 35314591, 2022). "Therefore, Atox1-knockout in mice blunts the induction of SOD3 by angiotensin II and, thus, exacerbates increased vasoconstriction in mesenteric arterioles and hypertension induced by angiotensin II." (PMID 35277059, 2022). "Considering the associations between SOD3 Ala58Thr and plasma SOD activity and between eNOS Glu298Asp and NOx concentration, the association between the polymorphisms and hypertension was investigated in a case-control population, including 343 hypertensive patients and 290 normotensive controls." (PMID 24944642, 2014). "The concordance between decreased SOD activity and NOx concentration, combined with the genotypes of SOD3 Ala/Ala and/or eNOS Glu/Glu in hypertensive patients, may be useful in directing the antioxidant therapy of hypertension." (PMID 24944642, 2014). "Importantly, increasing SOD3 levels in various experimental disease models, e.g., chemically induced diabetes, hypertension, and inflammatory arthritis, reduced oxidative stress and improved disease state, thereby placing SOD3 as a central therapeutic target." (PMID 23624605, 2013). "Moreover, when other antioxidant-related gene polymorphisms (SOD2, SOD3, PON1, and GSTT1) are present, GPX3 rs3828599 is more strongly associated with the incidence of hypertension and is positively associated with coronary artery disease and with the severity of coronary atherosclerosis." (PMID 41152890, 2025). "Similar to our study, previous research has also demonstrated the association of the rs13306703 and rs8192288 variants of SOD3 with various non-neoplastic conditions, including cerebral infarction, essential hypertension, and chronic obstructive pulmonary disease." (PMID 39589950, 2024).
Hypertension (continued). "Those with co-morbidities such as diabetes and hypertension are in a state of oxidative stress, and infection with COVID-19 increases this oxidative stress, overwhelming the oxidative system, as seen in the present study, with decreased SOD3 and increased GSTp1 levels." (PMID 35314591, 2022). "Moreover, reduced levels of SOD3 isoform were found to be correlated with increased ROS levels in the aorta of aged rats, whereas SOD3 overexpression has been shown to improve endothelial function in rat models of hypertension and heart failure." (PMID 32630452, 2020). "In particular, it has been shown that high amount of SOD3, the extracelular isoform, localized between the endothelium and the smooth muscle layer of the vessels, and its presence preserves vascular function in ageing, in hypertension and in heart failure models." (PMID 29707113, 2018). "Therefore, the concordance of decreased SOD activity and NOx concentration, combined with genotypes of SOD3 Ala/Ala and/or eNOS Glu/Glu in hypertensive patients, may be useful in directing the antioxidant therapy of hypertension." (PMID 24944642, 2014). "The structure of SOD3 is similar to SOD1, and upregulation of SOD3 is conducive to rid the vascular system of oxidative damage, alleviating the severity of hypertension and coronary arteriosclerosis." (PMID 36003910, 2022). "However, an association between SOD3 Ala58Thr and hypertension was not identified." (PMID 24944642, 2014). "Conversely, in norepinephrine-induced hypertension, the generation of vascular oxygen anions was unaffected in ATP7A mutant mice with impaired copper transport, a finding consistent with observations in SOD3 knockout mice." (PMID 39267854, 2024). "When SOD3 values of no co-morbidities, Diabetes and diabetes with hypertension were compared; there was a significance between DM vs no co-morbidities and DM/HT vs. no co-morbidities groups." (PMID 35314591, 2022). "Superoxide dismutase 3 (SOD3), the extracellular isoform with the lowest expression in neural cells, opposes the negative effects of hypertension in the brain by increasing NO bioavailability and regulating cerebral blood flow." (PMID 26746670, 2017).
breast carcinoma (20 papers, 2014 to 2025). "Background/Objectives: This study investigated the association between the rs13306703 and rs8192288 variants of the superoxide dismutase 3 (SOD3) gene and breast cancer (BC) in the Mexican population, conducting both genetic and in silico analyses." (PMID 39589950, 2024). "A low expression of SOD3 is associated with cancer incidence and poor prognosis in cancers such as lung cancer, breast cancer, pancreatic cancer, and prostate cancer." (PMID 36359248, 2022). "Disease states associated with SOD3 include diabetes mellitus, ischemic stroke, and renal disease, and SOD3 has been suggested as a potential target for several inflammatory diseases with mimetics a potential therapeutic for Breast Cancers." (PMID 39480826, 2024). "Furthermore, low expression of SOD3 in breast cancer is associated with reduced relapse free survival in all types of breast cancer." (PMID 30941174, 2019). "The gene-gene interactions demonstrated a significant four-variant interaction among rs406113 (GPX6), rs974334 (GPX6), rs105213 (OGG1) and rs2284659 (SOD3) (p-value = 0.0008) with high-risk genotype combination showing increased risk for breast cancer (OR = 1.75 [95% CI; 1.26-2.44])." (PMID 25416100, 2014). "We show that VEGF C and Sod3 are positively associated in human breast cancer." (PMID 25358638, 2014). "In breast cancer models, restoring SOD3 under VEGFC knockdown conditions enhances primary tumor development and metastasis, indicating a synergistic relationship between VEGFC and SOD3 in tumor progression." (PMID 41028519, 2025). "Although in silico analysis suggests reduced SOD3 gene expression in BC, it would be beneficial to perform direct gene expression analyses in our population and investigate whether the studied variants affect this expression and contribute to breast cancer risk." (PMID 39589950, 2024). "Overexpression of SOD3 inhibited breast carcinoma cell growth and invasion through reduced expression of heparanase." (PMID 33717151, 2021). "Few studies on breast cancer have shown that the overexpression of antioxidant SOD3 reduced breast cancer metastasis implicating the use of antioxidants to reduce ROS in cancer therapy." (PMID 33922139, 2021). "Overexpression of SOD3 in a human breast cancer xenograft or in the 4T1 syngeneic model led to reduced lung metastasis and longer survival." (PMID 30941174, 2019). "We have previously shown that expression levels of the extracellular form of SOD (EcSOD or SOD3) is significantly down-regulated in a majority of breast carcinomas and its expression levels inversely correlated with clinical stage." (PMID 29296173, 2017). "Differential expression analysis of breast carcinomas versus normal tissues showed that EcSOD (or SOD3) is significantly down-regulated in different types of breast carcinomas in two main datasets, TCGA and Curtis Breast." (PMID 29296173, 2017). "A four-way interaction found that between rs406113 on the GPX6 gene, rs974334 on the GPX6 gene, rs1052133 on the OGG1 gene and rs2284659 on the SOD3 gene predicts breast cancer with a testing balance accuracy of 0.5267." (PMID 25416100, 2014). "We identified Sod3 as a target of VEGF-C in breast cancer cells by demonstrating that it is required for VEGF-C-mediated cell survival in response to oxidative stress and for VEGF-C-mediated metastasis." (PMID 25358638, 2014). "We have found six polymorphisms in OGG1, GPX6, SOD3, TXN and XDH genes significantly associated with predisposition to breast cancer." (PMID 25416100, 2014). "Conversely, certain studies report elevated SOD3 expression in highly metastatic breast cancer cell lines, where it may promote migratory behavior." (PMID 41028519, 2025). "In breast cancer, the relationship between SOD3 expression and disease progression is complex." (PMID 41028519, 2025).
breast carcinoma (continued). "SOD3 expression is often downregulated in tumors due to hypermethylation of its CpG sites, a phenomenon observed in gallbladder, liver, prostate, lung, and breast cancers." (PMID 40558258, 2025). "Likewise, overexpression of an extracellular form of CuZnSOD (SOD3) reduced breast cancer metastasis in vivo." (PMID 37210781, 2023). "To further investigate which of the known VEGF-C receptors may mediate the increase in Sod3 expression and the antioxidant phenotype, we first determined the expression of the receptors in 66 cl4 mammary carcinoma cells." (PMID 25358638, 2014). "Indeed, knockdown of Nrp2 in the 66 cl4 mammary carcinoma cell line led to a significant decrease in Sod3 expression compared to control KD cells." (PMID 25358638, 2014). "Expression of VEGF C and Sod3 was assessed in human breast cancers." (PMID 25358638, 2014). "Interestingly, we found that expression of VEGFC and SOD3 positively correlate not only in breast cancer (using two different human data sets) (Bittner Multi-cancer data set, unpublished data, 1 January 2006) but also in kidney and cervical cancers (Bittner Multi-cancer data set)." (PMID 25358638, 2014). "We identified Sod3 as a critical mediator of VEGF-C-induced metastasis, and we provide evidence that the VEGF-C-Sod3 axis plays a role in human breast cancers." (PMID 25358638, 2014). "Importantly, Sod3 downstream of VEGF-C is required for tumor growth and metastasis in the mammary orthotopic xenograft model, providing evidence that VEGF-C mediates breast cancer metastasis in part through regulating ROS." (PMID 25358638, 2014).
diabetes (17 papers, 2013 to 2025). "Furthermore, the SOD3 p.R231G variant was also reported to be associated with diabetes mellitus (DM) and several kinds of diabetes complications, including polyneuropathy, cardiovascular disease, myocardial infarction, and insulin resistance in DM patients." (PMID 33879836, 2021). "Several biomarkers of oxidative stress are known to be altered at the onset of diabetes, and it has been suggested that a low SOD3 concentration provides evidence for reduced extracellular antioxidant defense against superoxide in the early development of DM." (PMID 39589950, 2024). "GFAP, Flt1, 8-OHdG and TNF-ɑ immunoreactivity were increased, and ɑ-SMA, PEDF and SOD3 immunoreactivity were decreased in the diabetic retina." (PMID 35015779, 2022). "This study identified a short-term effect of human SOD3 on diabetes-induced retinal changes in a diabetic rat model." (PMID 35015779, 2022). "A clinical study in patients with type 2 diabetes has shown significant positive relationships between serum SOD3 concentration and the duration of diabetes, carotid artery intimal−media thickness, the severity of nephropathy, and the severity of retinopathy." (PMID 35740095, 2022). "Plethora of studies suggests that SOD3 can be used as novel treatment strategy for various diseases such as cancer, diabetes, rheumatoid arthritis, chronic inflammation, aging and neurodegenerative diseases." (PMID 35155837, 2022). "The parameters which helped in identifying the severity, leading to poor prognosis, were neutrophil:lymphocyte higher than 4, high CRP, low SOD3 values and high GSTp1 values, and diabetes mellitus as a co-morbidity." (PMID 35314591, 2022). "Future studies will focus on addressing the long-term effect of SOD3 in the rat STZ-induced diabetes model." (PMID 35015779, 2022). "As a member of the antioxidant defense system, SOD3 has been noted to be downregulated in the serum and urine of patients with diabetes." (PMID 34513931, 2021). "We used the prospective Copenhagen General Population Study and Copenhagen City Heart Study and genotyped 95,871 individuals for the rs1799895 R213G variation in the SOD3 gene, of which 4498 had diabetes." (PMID 26844281, 2015). "Higher serum and urinary SOD3 levels were found in the groups of early CKD and diabetes with CKD than in the diabetes-alone patients." (PMID 35740095, 2022). "In our previous study, the serum and urinary SOD3 levels in three different groups of patients (diabetes alone, early CKD, and diabetes with CKD) were measured." (PMID 35740095, 2022). "The levels of SOD1, SOD2, and SOD3 in the three groups with diabetes were not significantly changed." (PMID 27830142, 2016). "Diabetes, being the most common non-communicable disease in the subcontinent, and COVID-19, being a state of high inflammatory state with significant oxidative stress, the effects of diabetes on the levels of SOD3 were assessed." (PMID 35314591, 2022).
Obesity (15 papers, 2020 to 2025). Accumulation of substantial excess body fat. "SOD3 knockdown in human adipocytes caused increased accumulation of TGs,64,71 and global SOD3 knockout mice exhibited increased obesity and insulin resistance." (PMID 37224770, 2023). "Additional genes involved in pathways closely related to the obesity phenotype highlighted by our analysis as potential candidates that play a role in male mice susceptibility to obesity are Cckar, Sod3, Med28, and Slit2." (PMID 33143653, 2020). "Additionally, supporting our findings, overexpression of SOD3 in adipose tissues in cases of diet-induced obesity was associated with blocking the development of obesity, fatty liver, and insulin resistance." (PMID 33924357, 2021). "A significant effect of obesity was detected on gene expression of antioxidant enzymes superoxide dismutases 1, 2 and 3 (Sod1, Sod2 and Sod3), since there was a significant increase in their mRNA levels in ScWAT in obese animals." (PMID 39576482, 2025). "Originally SOD family was related to obesity due to “its protective role as an antioxidant”, and high SOD3 concentration/activity is expected to neutralize the high levels of the superoxide anion (O2•−) effectively." (PMID 33924357, 2021). "The anti-obesity effects of SOD were demonstrated when mice received hydrodynamic injections of SOD3 plasmids." (PMID 32903449, 2020). "Several SNPs of the NRF2 gene have repercussions on certain antioxidant enzymes, for example, rs2234694 is related to SOD1, rs2536512 to SOD3, rs1056806 to GSTM1, rs4880 to SOD2 and rs1800668 to GPx1; all were found in obese patients and were associated with increased risk of obesity." (PMID 40428311, 2025). "Furthermore, the role of SOD family, especially SOD3, in lipid metabolism and obesity has been previously explained in mice, chicken, beef, dairy cattle, and pig." (PMID 39729475, 2024). "Notably, Sod3 knockout mice exhibited an altered phenotype characterized by increased obesity, insulin resistance, enlarged adipose tissue and elevated triglyceride accumulation." (PMID 38136160, 2023). "Over-expression of Sod3 in high-fat diet fed mice has been shown to block diet induced obesity." (PMID 33143653, 2020). "SOD3, which encodes an antioxidative enzyme with various functions, was found to promote HSC activation and fibrogenesis when deficient, whereas its overexpression in HFD-fed mice blocked the obesity, hepatic steatosis, and insulin resistance typically induced by this diet." (PMID 38565287, 2024). "Inheritance association models revealed that four SNPs to have a prediction value for developing obesity, namely GSTM1 rs1056806 (C/T), SOD2 rs4880 (A/G), SOD3 rs2536512 (A/G), and GPX1 rs1800668 (A/G)." (PMID 33924357, 2021). "The mRNA levels of obesity-related inflammation genes like F4/80, TNFα, CD11c, MCP1 and IL6 were lower in these SOD3-administered mice and hepatic de novo lipogenesis genes like SREBP1c, fatty acid synthase and Scd1 were higher in mice that were just given a high fat diet." (PMID 32903449, 2020).